IL17A (interleukin 17A)
Diseases named in the same sentence as IL17A in open-access papers (continued):
Sharing a sentence is not in itself a finding about the gene and the disease.
dermatitis (continued). "The promotion of IL-17A and IL-22 production induced by M. globosa may restrain the development of TSLP and inhibit the Th1/Th2 type skin inflammation." (PMID 40309262, 2025). "Notably, in cultured primary human keratinocytes (KC), IL-17A synergizes with IL-22 and tumor necrosis factor (TNF)-α to induce the expression of IL-36, a cytokine with critical involvement in skin inflammation." (PMID 39600699, 2024). "When S. aureus was inoculated on IL-17A and IL-17F double-knockout mice lacking IL-17 signaling, skin inflammation was attenuated compared to that in wild-type mice, whereas the number of S. aureus grown on the skin was comparable." (PMID 37124047, 2023). "HFD reduced mRNA levels of IL-17A, IL-17F, IL-22, IL-1β, tumor necrosis factor (TNF)-α, CXCL1, CXCL2, and keratin 16 and increased those of transforming growth factor (TGF)-β1 and cyclin-dependent kinase inhibitor 1A in imiquimod-induced dermatitis." (PMID 37762500, 2023). "Our observations point to IL-17A, but not IL-4, contributing to the development and/or maintenance of the skin inflammation described in WAS−/− animals." (PMID 35265075, 2022). "In this regard, the lack of IL-17A is known to reduce skin inflammation and suppress IL-4 and IgE production." (PMID 36362286, 2022). "However, in this study, we observed robust Th17 responses as well as expression of IL-17A signature genes (i.e., S100a8, S100a9, CAMP, and LCN2) in the skin of Nfkbiz−/− mice with spontaneous dermatitis." (PMID 28740238, 2017). "Furthermore, IL-17A target genes (i.e., S100a9, S100a8, CAMP, and LCN2) were remarkably upregulated in the skin of Nfkbiz−/− mice with dermatitis." (PMID 28740238, 2017). "In summary, our results from the analysis of a mouse model of dermatitis revealed that skin-derived inflammatory cytokines can induce amyloid deposition in the liver and spleen, and that the administration of JAK inhibitors and, even more, IL-17A ablation, reduced amyloidosis." (PMID 35628531, 2022). "Additionally, deletion of Brd4 in follicle stem cells also rendered them sensitive to cell death, which in turn triggered the activation of γδ T cells and production of potent inflammatory cytokines, including IL-17A, IL-17F, and IFN-γ, that subsequently mediate skin inflammation." (PMID 36256455, 2022). "Mice lacking IL-17A exhibited reduced dermatitis together with less IL-4 and IgE production." (PMID 34531749, 2021). "When these LN cells were stimulated by anti-CD3 with or without anti-CD28 antibody (Ab), more IL-17A was secreted by LN cells of CD4CreTTPf/f mice than that of WT mice, suggesting a correlation between IL-17 and the development of dermatitis in the aging CD4CreTTPf/f mice." (PMID 32922402, 2020). "The lack of IL-17A reduced dermatitis and IL-4 production as well as IgE production." (PMID 32075269, 2020). "Similarly, knockout of IL‐17A or IL‐22 on the Flgft/ft background did not ameliorate skin inflammation." (PMID 30937919, 2019). "Together, dual blockade of IL-17A and IL-36R in the form of a bispecific antibody may have advantages in blocking the overlapping and non-overlapping functions of these two cytokines in skin inflammation that could not optimally be curtailed with single mAbs." (PMID 39600699, 2024). "A negative TCF4/IL-17C/ TNF-a/ IL-17A feedback loop decreases TCF4 in an IL-17RA/RE-dependent manner and is further amplified by IL-17C/TCF4 regulation of ZC3H12A and IL-17C regulation of NFKBIZ, resulting in self-sustaining skin inflammation." (PMID 38470486, 2024).
experimental autoimmune encephalomyelitis (184 papers, 2008 to 2025). An autoimmune demyelinating disease of the central nervous system that is produced experimentally in animals by the injection of homogenized brain or spinal cord in Freund's adjuvant. "Mice with IL-17A or IL-17A receptor deficiency are less predisposed to experimental autoimmune encephalomyelitis (EAE) induction; these mice develop milder symptoms compared to non-deficient mice." (PMID 38638687, 2024). "AP-ctCTLA-4 reduced IL-17A expression under Th17 differentiation conditions in vitro and ameliorated experimental autoimmune encephalomyelitis, with decreased numbers of pathogenic IL-17A+GM-CSF+ CD4 T cells." (PMID 34452095, 2021). "Deficiency or pharmacologic blockade of FXII renders mice less susceptible to experimental autoimmune encephalomyelitis (a model of MS) and is accompanied by reduced numbers of interleukin-17A-producing T cells." (PMID 27188843, 2016). "Whereas Tiam1 genetic deficiency weakens IL-17A expression partially and inhibits the development of experimental autoimmune encephalomyelitis (EAE), deletion of Rac1 in T cells exhibits more robust effects on Th17 cells and EAE." (PMID 27725632, 2016). "Previous reports demonstrated that IL-18 promoted IL-17A secretion in a cecal slurry-induced peritonitis model and, along with IL-23, induced T cells to produce IL-17A in an experimental autoimmune encephalomyelitis model." (PMID 40777291, 2025). "Knockout ACT1 (a key transcription factor for signals mediated by IL-17A, IL-17F, and IL-17C) reduced the number of infiltrating inflammatory cells and ameliorates experimental autoimmune encephalomyelitis." (PMID 37581321, 2024). "ICOS-deficient mice develop increased numbers of Vγ4+ cells than WT controls, and experimental autoimmune encephalomyelitis is more severe in these mice as a result of increased IL-17A levels." (PMID 36480166, 2023). "IL-17A was reported to modulate the severity of myelin oligodendrocyte glycoprotein (MOG)-induced experimental autoimmune encephalomyelitis (EAE), although the magnitude of this effect varies substantially between studies." (PMID 36271145, 2022). "Studies on experimental autoimmune encephalomyelitis, an animal model of MS, highlighted the role of Th17 lymphocytes, characterized by interleukin 17A (IL-17A) secretion, as strong inducers of pro-inflammatory responses." (PMID 35572543, 2022). "Studies also indicate that there is a relationship between IL-33 and the Th17 response, one study reported that IL-33 was able to suppress IL-17A production by attenuating experimental autoimmune encephalomyelitis." (PMID 34324507, 2021). "IL-17A was reported to have an anti-apoptotic effect in experimental autoimmune encephalomyelitis (EAE) or under the other conditions." (PMID 32632545, 2020). "In stark contrast, using experimental autoimmune encephalomyelitis, we show that IL-17ACre–mediated deletion of Tbx21 prevents the conversion of Th17 cells to IL-17A/IFN-γ double-producing cells as well as Th1-like IFN-γ+ ex-Th17 cells." (PMID 27183623, 2016). "It was previously shown that daily intra-peritoneal doses of these drugs were able to reduce the clinical severity of a murine model of IL-17A-mediated experimental autoimmune encephalomyelitis (EAE)." (PMID 27658195, 2016). "We generated novel IL-17A reporter mice to investigate expression of IL-17A during Klebsiella pneumoniae infection and during experimental autoimmune encephalomyelitis, conditions previously demonstrated to potently induce IL-17A production." (PMID 22768117, 2012). "Similarly, the ubiquitin-specific protease USP25 was shown to deubiquitinate TRAF6 and prevent excessive IL-17A-induced signaling and IL-17A-dependent experimental autoimmune encephalomyelitis (EAE)." (PMID 40821838, 2025).
experimental autoimmune encephalomyelitis (continued). "Inducible T cell costimulator (ICOS) signaling is important in thymic development of IL-17A–producing γδ T cells and function during experimental autoimmune encephalomyelitis, while the function of PD-1 on these cells is unknown." (PMID 36480166, 2023). "It has recently been demonstrated in experimental autoimmune encephalomyelitis (EAE) that IL-17A recruits IL-1β-secreting myeloid cells that prime pathogenic γδT17 and Th17 cells, whereas mice with HIF-1α-deficient T cells are resistant to induction of Th17-dependent EAE." (PMID 36961533, 2023). "We synthesized the AP-conjugated cytoplasmic domain of CTLA-4, AP-ctCTLA-4, which showed significant suppression of IL-17A and induction of Foxp3 in vitro as well as the alleviation of experimental autoimmune encephalomyelitis (EAE), with reduced levels of pathogenic IL-17A+GM-CSF+ CD4 T cells." (PMID 34452095, 2021). "Indeed, IL-23p19−/− mice, IL-17A−/− mice, and mice treated with anti-IL-17A are resistant to the induction of experimental autoimmune encephalomyelitis (EAE), a mouse model of MS." (PMID 33968012, 2021). "The findings from these approaches suggested a role for T cell p38 signaling in thymocyte development, TCR-induced proliferation and apoptosis, IFN-γ, IL-2, and IL-17A production, and autoimmune diseases such as collagen-induced arthritis and experimental autoimmune encephalomyelitis." (PMID 28011639, 2017). "Moreover, IP knockout mice had delayed onset of a Th17-associated neurological disease, experimental autoimmune encephalomyelitis (EAE), and reduced infiltration of IL-17A-expressing mononuclear cells in the spinal cords compared to wild type mice." (PMID 22590492, 2012). "In another study, PPARα-KO mice presented increased IL-17A+CD4+ T-cell (Th17) generation, resulting in increased pathological features of murine experimental autoimmune encephalomyelitis (EAE)." (PMID 39910334, 2025). "In a mouse model of experimental autoimmune encephalomyelitis (EAE), IL-23 drives the expansion of the IL-17A+ CD4+ T-cell population." (PMID 36763636, 2023). "A study in a model of experimental autoimmune encephalomyelitis in mice found that Hypericum perforatum extract in combination with gold nanoparticles decreased levels of IFN-γ, IL-17A and IL-6 and increased those of TGF-β, IL-10 and IL-4." (PMID 37687297, 2023). "Employing Il17aCreRosa26YFP fate reporter mice, we previously demonstrated that IL-17A-producing Th cells can produce IFN-γ alongside IL-17A, transitioning into IFN-γ-producing exTh17 cells that lose IL-17A expression in experimental autoimmune encephalomyelitis (EAE)." (PMID 39379604, 2024). "In the experimental autoimmune encephalomyelitis (EAE) model, the transcription of Th1 and Th17-specific cytokine genes interferon gamma (Ifng) and interleukin 17A (Il17a) was upregulated in optic nerve, and decreasing Ifng expression had a protective effect on optic neuritis in EAE mice." (PMID 38375484, 2024). "Although IL-17A is thought to be immunopathogenic in the brain during such diseases as experimental autoimmune encephalomyelitis, its role in CNS infections is not well described." (PMID 36040029, 2022). "In this study, we showed that Cd226−/− mice were resistant to myelin oligodendrocyte glycoprotein peptide 35-55 (MOG35−55)-induced experimental autoimmune encephalomyelitis (EAE) with highly expressed IL-10+CD4+ T cells and downregulated IL-17A+CD4+ T cells when compared with wild-type (WT) mice." (PMID 32983109, 2020). "Other studies that examined mice with T cells lacking p38α alone or both p38α and p38β, however, did not observe substantial effects on IFN-γ and IL-17A production or experimental autoimmune encephalomyelitis." (PMID 28011639, 2017). "According to evidence in experimental autoimmune encephalomyelitis (EAE) animal models, vitamin A inhibits T-helper 17 cells, and a lack of T-helper 17’s main cytokine, interleukin-17A (IL-17A), enhances cognitive deficits in mice." (PMID 40337414, 2025).
lung cancer (175 papers, 2012 to 2026). A malignant neoplasm involving the lung. "They thought IL-17A and recruited neutrophils cause lung cancer inflammation and shape the lung cancer immune microenvironment where T cells function are suppressed, leading to the resistance to PD-1 immune checkpoint blockade." (PMID 41254689, 2025). "Studies have also indicated an association between various polymorphisms in the IL-17A gene and an elevated risk of lung cancer." (PMID 38983267, 2024). "Our findings suggest that IL-17A derived from lung cancer cells affects osteoclast differentiation by regulating OCP apoptosis, indicating that IL-17A is a potential therapeutic target for cancer-associated bone resorption in patients with lung cancer." (PMID 38394046, 2024). "Murine models of KRAS-driven lung cancer suggest that IL-17A and IL-17A-expressing lymphocytes mediate tumor-associated inflammation and tumor cell proliferation." (PMID 35883573, 2022). "LD analysis indicates that IL-17A rs2275913 and IL-17A rs8193037 were associated with susceptibility to lung cancer." (PMID 36300118, 2022). "There is evidence that levels of IL-17A and IL-17A-producing cells in the tumor microenvironment and bloodstream are associated with disease progression in lung cancer patients." (PMID 35883573, 2022). "Smoking is related to IL-17A upregulation in NSCLC through affecting promoter polymorphisms of the IL-17A gene that enhance the susceptibility to lung cancer." (PMID 33802737, 2021). "IL-17a is mainly produced by Th17 cells, which is closely associated with the development of various types of tumors, including lung cancer." (PMID 32554855, 2020). "Additional evidence suggests that IL-17A drives EMT via STAT-3 signaling in lung cancer, perhaps a mechanism to explain the association with poor prognosis." (PMID 28402963, 2017). "HC may inhibit PI3K/Akt/mTOR and ERK1/2 signaling pathways in human lung cancer cells, while IL17A can inhibit PI3K/Akt/mTOR-mediated autophagy, which causes lung inflammation and fibrosis." (PMID 35891565, 2022). "In addition, interactions between IL-17A SNPs and tobacco smoking were reported to be correlated with the risk of lung cancer." (PMID 33802737, 2021). "In conclusion, our study for the first time provided solid evidence that long-term PM2.5 exposure could enhance the risk of NSCLC through promoting the expression of IL-17a, thereby increasing lung cancer cell proliferation and metastasis." (PMID 32554855, 2020). "We therefore investigated whether the association with survival of the IL-6 plus IL-17A classifier and the IL-6, CRP and IL-17A classifier was specifically associated with survival in stage IA lung cancer patients." (PMID 28402963, 2017). "However, high levels of IL-17A expression, measured by immunohistochemistry in non-small-cell lung tumor samples, has been associated with poor lung cancer survival." (PMID 28402963, 2017). "In lung cancer, not only is IL-17 a potential diagnostic marker, but it also may act as a novel therapeutic target." (PMID 25110397, 2014). "Lung cancer is closely associated with chronic inflammation, and previous studies have provided evidence that local lung flora can promote inflammation and tumor cell proliferation by activating lung-resident γδT cells and releasing specific immune mediators such as IL-17A." (PMID 37978543, 2023). "Moreover, IL-17A rs2275913 and IL-17A rs8193037 had associated with predisposition to lung cancer." (PMID 36300118, 2022). "In lung cancer, IL-17A promotes osteoclastogenesis by regulating osteoclast precursor apoptosis, thus enhancing osteoclast survival and contributing to bone destruction." (PMID 40536951, 2026). "In lung cancer, IL-17A/F promotes the adoption of an M2-like phenotype by macrophages, which enhances tumor cell migration, proliferation, and angiogenesis, thereby supporting tumor progression." (PMID 40536951, 2026).
lung cancer (continued). "IL-6, IL-7, IL-10, and IL-17A levels were elevated in the plasma of lung cancer patients as compared to those in healthy controls; thus, indicating higher concentrations of inflammatory mediators in patients." (PMID 40040705, 2025). "In lung cancer studies, overexpression of IL-17A has been found to accelerate tumor progression by inducing inflammation." (PMID 40370457, 2025). "Ding and colleagues identified direct links between IL‐17A, various serum metabolites, and the development of lung cancer, highlighting the significant impact of inflammatory and metabolic imbalances on the pathogenesis of cancer." (PMID 40704775, 2025). "Considering the established role of IL-17A in lung cancer development, we investigated the effects of IL-17A derived from lung cancer A549 cells on osteoclast differentiation." (PMID 38394046, 2024). "For example, IL-17A-stimulated M2 macrophage polarization can facilitate cell migration, angiogenesis, and tumor growth in lung cancer." (PMID 38430256, 2024). "IL-17A can promote the development of lung cancer by directly inhibiting the apoptosis through the ROS/Nrf2/p62 pathway leading to increased PD-L1 expression in NSCLC cells." (PMID 39906741, 2024). "Interleukin-17A (IL-17A) affects osteogenesis by regulating the survival of osteoclast precursors (OCPs) and is enriched in lung cancer cells." (PMID 38394046, 2024). "In lung cancer, IL-6 and IL-17 upregulate RORγt through STAT3 signaling mechanisms in order to produce IL-17 isoforms, IL-17A/F." (PMID 38279220, 2024). "Previous studies reported high IL-17A expression in lung cancer cells and in the serum of patients with NSCLC that was associated with poor prognosis." (PMID 38394046, 2024). "Some studies have reported the overexpression of IL-17A in lung cancer tissues and its promotion of lung cancer progression and metastasis." (PMID 39257908, 2024). "In summary, we showed that inhibiting IL-17A expression in lung cancer A549 cells inhibited osteoclast differentiation, as IL-17A deficiency induced OCP apoptosis in the early stage." (PMID 38394046, 2024). "Some studies have found that IL-17A promotes the secretion of CCL20 by cancerous cells, implicating the CCL20/CCR6/IL-17 axis as a potential new therapeutic target for lung cancer." (PMID 39906741, 2024). "The study reported that inhibiting IL-17A expression in A549 lung cancer cells suppressed osteoclast formation." (PMID 39125732, 2024). "A study investigated the role of interleukin-17A (IL-17A) derived from lung cancer cells in osteoclastogenesis, which is crucial for bone metastasis." (PMID 39125732, 2024). "In agreement with our data, anti–PD-1 treatment of an autochthonous lung cancer mouse model increases IL-17A–producing γδ T cells and CD4+ T cells, which correlates with suppression of cytotoxic CD8+ T cells." (PMID 36480166, 2023). "Airborne particulate matter such as PM2.5 also regulates tumor cell proliferation, metastasis and EMT by promoting the expression of IL-17A in lung cancer tissues." (PMID 37978543, 2023). "It has also been shown that treatment with a neutralizing anti-IL-17A antibody can reduce the angiogenesis of the tumor as well as reduce the inflammatory response, thereby reducing the growth of lung cancer progression." (PMID 37409245, 2023). "The purpose of the present study was to investigate the effect of IL-17A on the biological behaviour of lung cancer cells and the relative mechanism." (PMID 36349316, 2022). "Consistent with our meta-analysis, strong evidence was assigned to IL-17A rs2275913 in lung cancer, cervical cancer, RA, SpA, and IL-17A rs8193037 in lung cancer." (PMID 36300118, 2022). "There have been several relevant studies on the effect of IL-17A on lung cancer, but what changes occur in tumor cells after IL-17A stimulation and the mechanism of the changes remain to be elucidated." (PMID 36349316, 2022).